CXCL10 (C-X-C motif chemokine ligand 10)
Diseases named in the same sentence as CXCL10 in open-access papers (continued):
Sharing a sentence is not in itself a finding about the gene and the disease.
colon carcinoma (continued). "In human colon cancer samples, FGFR4 and CXCL10 expression was positively correlated with CAF marker expression." (PMID 40447617, 2025). "Clinical samples of colon cancer patients were evaluated to assess the correlation between the expression of FGFR4, CXCL10, and CAF markers." (PMID 40447617, 2025). "The expression levels of FGFR4, CXCL10, and CAF markers were significantly upregulated in colon cancer tissues compared with those in normal tissue samples." (PMID 40447617, 2025). "Conversely, protective genes such as PAEP, TAP2, CXCL10, and IRF1 were notably down-regulated in colon cancer cells." (PMID 40959081, 2025). "The recruitment of T cells in human colon cancer tissue was impacted by CXCL9 and CXCL10, whose expression is regulated by H3K27me3 repression marks." (PMID 37273004, 2023). "In the current study, we demonstrated that VIP antagonist enhanced M1 markers TNF-α, iNOS, and CXCL10, reduced Mrc-1 mRNA expression, and increased phagocytic ability against CT26 colon cancer cells in mouse macrophage RAW264.7 cells incubated with CT26-CM." (PMID 36650220, 2023). "CXCR3+ NK-cell and CD8+ T-cell tumoral infiltration, directed by CXCL9 and CXCL10, can delay primary tumor growth in MC38 colon carcinoma and TC-1 epithelial carcinoma mouse models when treated with heterodimeric IL-15." (PMID 36030223, 2022). "Another example was the oncolytic adenovirus with an inserted CXCL10 gene (Adv-CXCL10), which enhanced the recruitment of CXCR3+ T cells into the colon tumor microenvironment corroborated with increasing the efficacy of PD-1 antibody." (PMID 36366543, 2022). "However, in contrast to its ligands, CXCL9, CXCL10, and CXCL11, the protein expression of the CXCR3 chemokine receptor protein in colon cancer tissue could be associated with increased tumor size, the occurrence of lymph node or distant metastasis, and poor survival." (PMID 36428508, 2022). "Cumulative evidence suggested that increased expression levels of CXCL9 and CXCL10 induced tumor-infiltrating CD8+T cells, leading to reduced cancer progression or metastasis and enhanced survival in ovarian and colon cancer patients." (PMID 30034618, 2018). "Initial quantitative PCR studies of ex vivo tissue specimen showed that CXCL9, CXCL10 and CXCL11 are significantly increased in human colon tumors compared to unaffected tissue." (PMID 29671006, 2018). "We previously identified chemokines CXCL9, CXCL10, and CXCL11, as well as GZMB (Granzyme B), as part of a prognostic gene signature in colon cancer." (PMID 29163806, 2017). "The expression of CXCR3 receptors by human and murine colon carcinoma cells has led us to determine the ability of the corresponding ligands (mouse CXCL9, CXCL10 and CXCL11) to induce their migration in vitro." (PMID 19436305, 2009). "Furthermore, the CXCL-10/CXCR3 axis was shown to enhance tumorigenicity and EMT induction in colon cancer cells." (PMID 40447617, 2025). "Next, we used AOM/DSS-induced colon cancer model to determine whether CCL5 and CXCL10 are required for CRC development." (PMID 40749055, 2025). "Interestingly, in a colon cancer mouse model, the immune-suppressive effect of TGF-β1 has been shown to be involved in repression of CXCL9 and CXCL10 expression in CAFs, which subsequently inhibited the recruitment of effector T cell infiltration into tumors." (PMID 38580966, 2024). "T helper 1-type chemokines CXCL9 and CXCL10 are silenced by PRC2 in ovarian and colon cancer." (PMID 35169119, 2022). "However, there have also been reports of CXCL9, CXCL10, and CXCL11 that promote tumor proliferation in colon cancer, esophageal adenocarcinoma, and head and neck cancer by promoting inflammation or other mechanisms." (PMID 32685487, 2020). "Along that line, high expression of CXCL9 and CXCL10, but not CXCL11, was associated with the attraction of memory CD8 T-cells with a specific TCR repertoire in colon cancer, indicative of good prognosis." (PMID 29163806, 2017).
colon carcinoma (continued). "Furthermore, we found that colon cancer tissues exhibited higher expressions of CCL20 and CXCL16, but similar expressions of CCL21 and CXCL10 as compared with unaffected tissue, which is in line with previous studies." (PMID 27517754, 2016). "By evaluating histological samples from human colon cancer metastases in the liver, we observed that numerous HB-EGF/CXCR4-positive macrophages, which expressed both the M1 CXCL10 and the M2 CD163 markers, indicating a mixed M1/M2 microenvironment, infiltrated metastatic cancer cells." (PMID 20946648, 2010). "FGFR4 expression was significantly positively correlated with that of CXCL10 (Pearson’s R = 0.32; P < 0.001) and CAF markers, including α-SMA (Pearson’s R = 0.43; P < 0.0001), PDGFR-β (Pearson’s R = 0.46; P < 0.0001), and FAP (Pearson’s R = 0.32; P < 0.001) in colon cancer samples." (PMID 40447617, 2025). "CXCL9 and CXCL10 are endogenous tumor angiogenesis inhibitors and high levels of CXCL9 and CXCL10 promote increasing numbers of tumor-infiltrating CD8+ T cells and reduce the level of cancer metastasis and improve survival rate of patients with ovarian or colon cancer." (PMID 36387070, 2022). "Previously, we found that in colon cancer, RFX1 showed a negative trend in correlation with the expression of key chemokines (CXCL9 and CXCL10) that induce the recruitment of CD8+ T cells to the tumor microenvironment." (PMID 41425715, 2025).
co-infection (53 papers, 2011 to 2025). "To further demonstrate the causal relationship between IFNγ and CXCL9/CXCL10 induction in the co‐infected mice, we performed co‐infection in IFNγ−/− mice." (PMID 29113976, 2018). "In addition, the expression levels of SOCS-6, which is a regulator of the JAK-STAT pathway and of CXCL10, which is an interferon-γ-induced protein, were associated with viral and bacterial co-infection and pneumonia severity." (PMID 35986232, 2022). "Similar to what we observed for SARS-CoV-2, samples with a viral coinfection had higher nasal CXCL10 than predicted by RV infection alone, especially when the coinfecting virus was present at a high viral load." (PMID 38949638, 2024). "In this study, we analyzed the performance of these two tests in TB patients with HIV co-infection and found that the proportion of indeterminate results of CXCL10 mRNA release assay was lower than that of T-SPOT.TB test." (PMID 35432271, 2022). "The expression of chemokine (C-X-C motif) ligand 10 (CXCL10) was shown to be indirectly modulated by miR-200a-3p by targeting suppressor of cytokine signaling-6 (SOCS-6) to regulate the immune response to co-infection." (PMID 35986232, 2022). "The results suggested that the overall diagnostic performance of the CXCL10 mRNA release assay was consistent with the T-SPOT.TB test, and it presented a better positive rate in HIV co-infection patients." (PMID 35432271, 2022). "Among the 14 TB patients with HIV co-infection, all presented valid CXCL10 mRNA release assay results, while 3 patients presented indeterminate results in T-SPOT.TB test." (PMID 35432271, 2022). "In this study, although RSV infection strongly mitigated by macrophages after 24 hpi, we have shown that bacterial co-infection contributes to alter the timing and extent of innate immune response, as illustrated by CXCL10 expression." (PMID 29215596, 2017). "Sustained high CXCL9/CXCL10 in DR-TB may reflect T-cell exhaustion, while IL-21 deficiency in HIV co-infection could impair B-cell responses, promoting immune evasion." (PMID 41007639, 2025). "However, in a subgroup of 14 TB patients with HIV co-infection, the molecular CXCL10 mRNA test showed a significantly higher positive rate (92.9%) than T-Spot.TB (61.5%; p = 0.029)." (PMID 36832246, 2023). "However, among TB patients with HIV co-infection (n = 14), CXCL10 mRNA release assay presented significantly higher positive rate [92.9% (66.1–99.8%) vs. 61.5% (31.6–86.1%), p = 0.029] than those of T-SPOT.TB." (PMID 35432271, 2022). "HIV co-infection rate is significantly higher in participants with indeterminate results of CXCL10 mRNA release assay and T-SPOT.TB test (33.3%, 3/9) than that in participants with valid results of CXCL10 mRNA release assay and T-SPOT.TB test (2.22%, 11/496) (p = 0.0013)." (PMID 35432271, 2022). "Therefore, we further compared the diagnostic performance of CXCL10 mRNA release assay and T-SPOT.TB assay among TB patients with HIV co-infection." (PMID 35432271, 2022). "We conclude that increased CXCL10 in hepatocytes, as a result of co-infection of hepatocytes with HIV and HBV, may be an important new target for treatments to reduce liver disease in people living with HIV and HBV and should be further investigated." (PMID 32898182, 2020). "Immunohistochemistry demonstrated CXCL10 expression in liver biopsy sections in association with inflammatory infiltrates in the portal regions in liver biopsies from people living with HIV-HBV co-infection but there was minimal expression of CXCL10 in healthy controls." (PMID 32898182, 2020). "However, we propose that CXCL10 remains an important mediator of liver disease in HIV-HBV co-infection, even in the setting of ART." (PMID 32898182, 2020).
co-infection (continued). "In vivo, we also showed that CXCL10 production in HIV-HBV co-infection was localised to areas of inflammatory infiltration in the periportal regions of liver tissue, but was almost entirely located in hepatocytes, rather than in the infiltrating lymphocytes or neutrophils." (PMID 32898182, 2020). "In the RR/HIV group, CXCL10 is negatively correlated with the IL-12 family member IL-23, suggesting that co-infection may induce different pathways and different inflammatory mechanisms could be modulated." (PMID 32849508, 2020). "We demonstrated that endogenous miRNA-200a-3p, whose expression was synergistically induced following co-infection, indirectly regulates CXCL10 expression by targeting suppressor of cytokine signaling-6 (SOCS-6), a well-known regulator of the JAK-STAT signaling pathway." (PMID 27922126, 2016). "Virus detection and load correlated with the nasal interferon response biomarker CXCL10, and the previously reported discrepancy between SARS-CoV-2 viral load and nasal interferon response was explained by viral coinfections." (PMID 38949638, 2024). "We demonstrated that co-infection of hepatocytes in vitro with HIV and HBV significantly increased production of CXCL10." (PMID 32898182, 2020). "Previous work in two separate models—HIV-HCV co-infection and HIV infection of astrocytes —demonstrated that the HIV tat protein, a potent transcriptional activator, can directly induce CXCL10 expression." (PMID 32898182, 2020). "This occurs through the induction of higher splenic IFNγ during co‐infection, leading to higher local levels of CXCL9 and CXCL10 that retains the CXCR3‐expressing CD8+ T cells in the spleen." (PMID 29113976, 2018). "We also observed increased positive staining of alpha chemokine CXCL10, a well-known marker of chronic liver inflammation in HIV/HCV co-infection that shows a TLR4-mediated pro-apoptotic effect on hepatocytes." (PMID 29361613, 2018). "Co‐infection with CHIKV induced higher splenic IFNγ levels that lead to high local levels of CXCL9 and CXCL10." (PMID 29113976, 2018). "Our study suggests co-infection leads to overexpression of miR-200a-3p, which in turn targets and downregulates the JAK-STAT regulator SOCS-6 and consequently increases CXCL10 (IP-10) expression." (PMID 27922126, 2016). "Both the CXCL10 mRNA release assay and the T-SPOT.TB assay are based on the host immune response to M.tb-specific antigens, and previous study identified HIV co-infection as the risk factor for false-negative and indeterminate IGRA results." (PMID 35432271, 2022). "The formula for Model 1 is as follows: Logit (p)=-2.295 + 2.402×CXCL13 + 1.270 × CXCL10-148 ×CXCL8 + 2.252 ×Whether there are symptoms or not -1.534 × HIV co-infection+0.917×sero-TRUST titer." (PMID 41221293, 2025). "The sample size of TB patients with HIV co-infection was not large enough; thus, the power for evaluating the performance of CXCL10 mRNA release assay in this population was decreased, and further validation is needed in a larger sample size of HIV co-infected population." (PMID 35432271, 2022). "In individuals with co-infection, significant negative correlations between egg counts and CXCL10 secretion were found in cell cultures stimulated with L3 (p<0.05) or ES antigen (p<0.01), however without any significant differences when compared with mono-infected individuals." (PMID 21909439, 2011). "The top three markers contributing most to overall network density by AUC in the subgroup of those without HIV-1 co-infection were CXCL10, C-reactive protein, and IFNα2, whereas the top three markers in the subgroup of those with HIV-1 co-infection were IL-17A, IL-1β, and TNFα." (PMID 34386782, 2021). "In contrast to the observations in human subjects that CXCL10 predicted TB disease state irrespective of HIV status, we observed a significant reduction of CXCL10 in the liver and plasma, but not the lung, of HIS mice in the setting of co-infection." (PMID 32373548, 2020).
pancreatic cancer (50 papers, 2013 to 2025). "The core gene C-X-C motif chemokine ligand 10 (CXCL10) exhibited a close association with the development of pancreatic cancer." (PMID 40129528, 2025). "Previous studies investigated the correlation between CXCL10 and pancreatic cancer; however, causal analysis and specific mechanism exploration remained unexplored." (PMID 40129528, 2025). "Consistent with previous studies, the expression of CXCL10 was increased in pancreatic cancer and linked with poor prognosis." (PMID 40129528, 2025). "Nonetheless, the role and underlying mechanisms of CXCL10 in the progression of pancreatic cancer remain inadequately understood." (PMID 40129528, 2025). "CXCL10 was the central gene, and its expression was significantly linked to the survival of patients with pancreatic cancer and their response to immune checkpoint inhibitors." (PMID 40129528, 2025). "The results found that the expression of CXCL10 in pancreatic cancer patients was significantly high, higher expression of CXCL10 was linked to worse prognosis in pancreatic cancer patients." (PMID 40129528, 2025). "Tumor-associated macrophages express CXCL10 in pancreatic cancer, and its acceptor CXCR3 is extremely expressed in T cells." (PMID 35685428, 2022). "With the exception of osteosarcoma and pancreatic cancer, high CXCL10 expression is associated with favorable patient outcomes in various cancer types including breast, ovarian, liver, colon, rectum, esophagus, thyroid, and head and neck cancers." (PMID 35207629, 2022). "We found an association of increased expression of CXCL9, CXCL10, and CXCL10 with decreased survival in pancreatic cancer and CXCL5 in cholangiocarcinoma." (PMID 35740353, 2022). "Recent studies have confirmed a stromal origin of CXCL10 in human tumors which is overexpressed in human pancreatic cancer and associated with poor survival of PAAD patients." (PMID 33681290, 2021). "In pancreatic cancer, high levels of CXCL10 were associated with elevated levels of M2 and M1 macrophages, gamma delta T cells, follicular helper T cells, neutrophils, activated natural killer cells, and CD8+ T cells when compared to low CXCL10 expression groups." (PMID 40129528, 2025). "This study used MR analysis to find the potential causal link between CXCL10 and pancreatic cancer." (PMID 40129528, 2025). "CCL4, CCL5, CXCL9, and CXCL10 are associated with CD8+ T cells in pancreatic cancer." (PMID 38887558, 2024). "In particular, the increased concentrations of IP-10/CXCL10 in the TIME of pancreatic cancer have been linked to the recruitment of Tregs to the tumor site, which, in turn, may contribute to disease progression." (PMID 37519820, 2023). "CXCL10 has been associated with an immunosuppressive phenotype in pancreatic cancer." (PMID 33540635, 2021). "This study not only demonstrated that the chemokine CXCL10 can serve as a prognostic marker for pancreatic cancer but also shed light on the role of the tumor microenvironment." (PMID 40063597, 2025). "Our findings indicate that CXCL10 potentially facilitates the progression of pancreatic cancer by modulating the expression of vascular endothelial growth factor A (VEGFA), thereby inducing macrophage polarization towards the M2 phenotype." (PMID 40129528, 2025). "CXCL10 is overexpressed in human pancreatic cancer and is related to the poor survival of patients with PAAD." (PMID 40129606, 2025). "This consistency implied the absence of any single dominant SNP influencing the relationship between CXCL10 levels and pancreatic cancer, affirming the reliability of the initial MR findings." (PMID 40129528, 2025). "CXCL10 can promote the migration of pancreatic cancer cells to sensory neurons and mediate the pain response in patients." (PMID 40129606, 2025). "The serum CXCL10 level in pancreatic cancer patients with lymph node metastasis is significantly higher than that in pancreatic cancer patients without lymph node metastasis." (PMID 40129606, 2025).